PIK3R1 (phosphoinositide-3-kinase regulatory subunit 1)
Diseases named in the same sentence as PIK3R1 in open-access papers (continued):
Sharing a sentence is not in itself a finding about the gene and the disease.
vascular malformation (4 papers, 2021 to 2025). A non-neoplastic disorder that is the result of defects of vascular morphogenesis. "A skin biopsy from the vascular malformation revealed the presence of two pathogenic in cis PIK3R1 variants, c.1699A>G (VAF 8%) and c.1703C>T (VAF 8%)." (PMID 40389643, 2025). "While most cases of overgrowth syndromes can be explained by gain-of-function mutations in PIK3CA, recent studies have reported PIK3R1 mutations in some patients with overgrowth syndromes and vascular malformations." (PMID 40389643, 2025). "The PIK3R1 variant is also listed in ClinVar (ID 376261) as “pathogenic” or “likely pathogenic” for somatic origin and has been frequently detected in vascular malformations and various cancers." (PMID 39859528, 2025). "The somatic mosaic PIK3R1 variants we describe in vascular malformations and overgrowth further extend our understanding of PIK3R1, whose genetic perturbation produces pleiotropic manifestations." (PMID 34040190, 2021). "Somatic PIK3R1 mutations cause overgrowth syndromes and vascular malformations." (PMID 40389643, 2025). "We used targeted, high-depth NGS to analyze Affected tissue from a cohort of individuals with vascular malformations, and thereby extend understanding of the role played by PIK3R1 in these clinically important disorders." (PMID 34040190, 2021). "Given the numerous variants identified in PI3K pathway components (PIK3CA, AKT1, and PTEN) in overgrowth, PIK3R1 is an excellent candidate gene for vascular malformations and overgrowth." (PMID 34040190, 2021). "PIK3R1 variation in the setting of vascular malformation with overgrowth has been rarely reported." (PMID 34040190, 2021). "Somatic PIK3R1 variation can also be attributed to genetic variation in the PI3K-AKT pathway and can induce vascular malformations and overgrowth." (PMID 34887920, 2021).
Autoimmunity (3 papers, 2021 to 2022). The occurrence of an immune reaction against the organism's own cells or tissues. "Of note, the loss-of-function mutations in PIK3R1 and PTEN lead to a similar clinical phenotype to that of GOF mutations in the PIK3CD gene, characterized by decreased B lymphocytes and naïve T lymphocytes, lymphoproliferation, and autoimmunity." (PMID 35990641, 2022).
clear cell carcinoma (3 papers, 2021 to 2025). "We found that PIK3R1 mutations mainly contribute to the development of low-stage endometrioid and clear-cell carcinomas with coexisting PTEN mutations." (PMID 39858051, 2025). "The patient carried a typical genomic profile of clear cell carcinoma including mutations in KRAS, PPP2R1A, and PIK3R1." (PMID 38686193, 2024). "Fieuws detected PIK3R1 mutations in 6.7% of clear-cell carcinomas and 2.4% of HGSOCs with no clinical characteristics given." (PMID 39858051, 2025).
common variable immunodeficiency (3 papers, 2021 to 2025). "We identified a novel heterozygous frameshift mutation (c.1710dup) in PIK3R1 in a patient with common variable immunodeficiency (CVID) who later developed slowly progressive Amyotrophic Lateral Sclerosis (ALS)." (PMID 40568112, 2025). "Similarly, activated PI3Kδ syndrome (APDS), due to PIK3CD or PIK3R1 mutations, and common variable immunodeficiency (CVID) have been associated with EBV-positive lymphomas, reflecting impaired immune regulation and defective viral clearance." (PMID 41367858, 2025).
endometrial tumors (3 papers, 2025). "Several studies have shown that PIK3R1 frequently coexists with PTEN and KRAS mutations in endometrial tumors." (PMID 39858051, 2025). "Interestingly, our prior study of samples from the Caris database indicated that in post-menopausal women, endometrial tumors harboring the CC genotype were enriched with multiple genomic alterations in the PI3 kinase pathway, including PTEN, PIK3CA, and PIK3R1." (PMID 40282446, 2025).
Hepatic steatosis (3 papers, 2021 to 2023). Steatosis is a term used to denote lipid accumulation within hepatocytes. "Finally, among the DEGs, some are also key regulators of hepatic lipid metabolism (e.g., PIK3R1, PPARG, S100A11), suggesting that alterations in TIA1 expression/activity also contribute to fatty liver disease development." (PMID 35406476, 2022).
Hernia (3 papers, 2020 to 2023). "Together, our results show that PIK3R1, PTPN11, TGFBR1, CDC42, and SOS1 are probably the most essential proteins involved in human hernia formation." (PMID 31910207, 2020).
metastatic melanoma (3 papers, 2012 to 2025). A melanoma that has spread from its primary site to another anatomic site. "Overall, in metastatic melanoma, the PI3K pathway is altered by somatic mutations in a wide array of genes including PIK3CA, MTOR, PIK3R1, PIK3R5, and IRS4." (PMID 22912864, 2012).
oligodendroglioma (3 papers, 2022 to 2023). A well-differentiated (WHO grade II), diffusely infiltrating neuroglial tumor, typically located in the cerebral hemispheres. "In the 23 oligodendroglioma cases, CIC (70%), PIK3CA (35%), PIK3R1 (26%), and FUBP1 (22%) were detected." (PMID 35626060, 2022). "Oligodendrogliomas showed alterations in PIK3CA (3/5) and PIK3R1 (2/5)." (PMID 35372034, 2022).
osteoarthritis (3 papers, 2016 to 2021). A noninflammatory degenerative joint disease occurring chiefly in older persons, characterized by degeneration of the articular cartilage, hypertrophy of bone at the margins and changes in the synovial membrane. "Our data provide evidence for the FGF-signaling cascade (FGFR3, FGF18, and PIK3R1) being causally involved in osteoarthritis." (PMID 34450027, 2021). "The PIK3R1 gene was suggested to have the potential to function as a pain-related regulator according to the genetic interaction analysis, and its expression level might be associated with osteoarthritis pathogenesis." (PMID 33343676, 2020).
osteoporosis (3 papers, 2018 to 2023). A condition of reduced bone mass, with decreased cortical thickness and a decrease in the number and size of the trabeculae of cancellous bone (but normal chemical composition), resulting in increased fracture incidence. "In addition, lncRNA LNC_000052 caused the malfunction of mesenchymal stem cells in osteoporosis via the miR-96-5p-phosphoinositide-3-kinase regulatory subunit 1 (PIK3R1) axis." (PMID 38041147, 2023). "This suggested that the related target molecules had an important role in GCK-treated osteoporosis, especially for the targets STAT3, PIK3R1, VEGFA, JAK2 and MAP2K1." (PMID 36430397, 2022).
ovarian serous cystadenocarcinoma (3 papers, 2020 to 2025). A malignant serous cystic epithelial neoplasm arising from the ovary. "Contrary to this conclusion, an ovarian serous cystadenocarcinoma analysis from TCGA revealed an association between high PIK3R1 expression and worse prognoses." (PMID 39858051, 2025). "We first conducted genomic analyses of 489 human ovarian serous cystadenocarcinomas using the Cancer Genomics Atlas (TCGA), which revealed an inverse relationship between LRRC4 and PIK3R1 expression." (PMID 32117780, 2020).
overgrowth syndrome (3 papers, 2021 to 2025). A group of syndromes caused by genetic birth defects that may lead to the development of malignancies. "Mutations in PIK3R1 have recently been identified in patients with overgrowth syndromes and complex vascular malformations." (PMID 40389643, 2025). "Recently, somatic PIK3R1 mutations have been discovered in patients with overgrowth syndromes and complex vascular malformations." (PMID 40389643, 2025). "While further studies are needed to validate these promising results, our findings pave the way for new therapeutic approaches in patients with overgrowth syndromes and vascular anomalies caused by PIK3R1 variants involving the iSH2 domain." (PMID 40389643, 2025). "We have identified somatic mosaic variants in PIK3R1 harbored within the disease-affected tissue of individuals with vascular anomalies and overgrowth syndromes." (PMID 38541623, 2024). "Like our study of missense variation, we aimed to understand the details underlying how INDELs associated with overgrowth syndromes may affect the stability and dynamics of PIK3R1." (PMID 38541623, 2024). "Somatic mosaicism of PIK3R1 and PIK3CA are associated with vascular anomalies and overgrowth syndromes." (PMID 38541623, 2024).
psoriasis (3 papers, 2013 to 2025). An autoimmune condition characterized by red, well-delineated plaques with silvery scales that are usually on the extensor surfaces and scalp. "PIK3CA/PIK3R1, central to the PI3K–AKT–MTOR pathway, has been linked to the progression from psoriasis to PsA." (PMID 40560578, 2025). "Many DEG-coded proteins (CCNA2, FYN, PIK3R1, CTGF, F3) and transcription factors (AR, TFDP1, MEF2A, MECOM) were identified as central nodes, suggesting their potential role in psoriasis pathogenesis." (PMID 24303025, 2013).
schizophrenia (3 papers, 2008 to 2025). A major psychotic disorder characterized by abnormalities in the perception or expression of reality. "Phosphoinositide-3-kinse regulatory subunit polypeptide 1 (PIK3R1), AT-binding transcription factor 1 (ATBF1), Lin-7 homolog b (Lin-7b) and calcium-independent phospholipase A2 gamma (IPLA2γ), had significantly altered expression in the STG in schizophrenia identified by microarray analysis." (PMID 18445270, 2008).
triple-negative breast carcinoma (3 papers, 2020 to 2024). An invasive breast carcinoma which is negative for expression of estrogen receptor (ER), progesterone receptor (PR), and human epidermal growth factor receptor 2 (HER2). "PIK3R1, frequently mutated in triple-negative breast cancer, has been associated with other genetic alterations and higher tumor mutational burden, indicating its significance for targeted therapies." (PMID 39204124, 2024). "From a molecular point of view, mutations in PIK3CA, PIK3R1 and PTEN genes are significantly more frequently found in MBC as compared to triple-negative breast carcinomas of no special type." (PMID 32127014, 2020).
Alcohol- (2 papers, 2008 to 2021). "Our findings highlight a previously unknown relevance of PIK3R1 genotypes for alcohol use disorders and might help discriminate individuals at risk for alcoholism." (PMID 18335044, 2008). "Taken together, our results indicate that variations in the PIK3R1 gene are associated with multiple aspects of alcohol risk drinking behaviour in male adolescents, suggesting a relevance of PIK3R1 genotypes for early onset of alcoholism in humans." (PMID 18335044, 2008).
amyotrophic lateral sclerosis (2 papers, 2023 to 2025). Amyotrophic lateral sclerosis (ALS) is a neurodegenerative disease characterized by progressive muscular paralysis reflecting degeneration of motor neurons in the primary motor cortex, corticospinal tracts, brainstem and spinal cord. "We identified a novel heterozygous pathogenic frameshift mutation (c.1710dup) in PIK3R1 in a patient with common variable immunodeficiency who developed slowly progressive Amyotrophic Lateral Sclerosis." (PMID 40568112, 2025).
asthma (2 papers, 2012 to 2024).
atopic dermatitis (2 papers, 2017). "Notably, the analysis of atopic dermatitis sequencing data revealed a crucial role for Pik3r1 in atopic dermatitis." (PMID 28787439, 2017).
autoimmune hepatitis (2 papers, 2021 to 2022). Hepatitis caused by autoantibodies. "As a consequence, 82 collective targets of celastrol and AIH were identified, among which PIK3R1, SRC, MAPK1, AKT1, and HRAS exhibited a closer association with autoimmune hepatitis." (PMID 35359864, 2022).
B-cell lymphoma (2 papers, 2021 to 2022). "Patients with APDS have a greater predisposition to B-cell lymphoma, for which the PIK3R1 involvement may be considered a risk factor for carcinogenesis." (PMID 35990641, 2022).
brain cancer (2 papers, 2017 to 2020). A primary or metastatic malignant neoplasm affecting the brain. "Compared to GBM, the genetic alteration of PIK3CA (2%) and PIK3R1 (0.3%) in medulloblastoma (MBM), which is the most aggressive malignant brain tumor that highly occurs in children and survival rate can reach 70% after active treatment, are less frequently observed." (PMID 32333246, 2020).
carcinosarcoma (2 papers, 2014 to 2020). A malignant tumor composed of a mixture of carcinomatous and sarcomatous elements. "We identified mutations in PIK3R1, a member of the PI3-kinase pathway that had not been previously implicated in carcinosarcomas, in 3 of 22 cases." (PMID 25233892, 2014).
dyslipidaemia (2 papers, 2020 to 2022). "In contrast, primary insulin signalling defects (in INSR or PIK3R1) do not result in dyslipidaemia or fatty liver." (PMID 35234134, 2022).
endometrial adenocarcinoma (2 papers, 2023 to 2024). "Using these models,it is shown that the mutations in Pik3ca and Pik3r1 cooperate with Pten loss to promote endometrial adenocarcinoma in mice." (PMID 37340596, 2023).
endometrioid ovarian carcinoma (2 papers, 2020 to 2025). "A maximum of six mutations was present in one patient with endometrioid ovarian carcinoma (MSH6, PIK3CA, FBXW7, PIK3R1, PITCH1, ERBB3 and PPP2R1A)." (PMID 32120793, 2020).
epilepsy (2 papers, 2024 to 2026). A brain disorder characterized by episodes of abnormally increased neuronal discharge resulting in transient episodes of sensory or motor neurological dysfunction, or psychic dysfunction. "In expression level validation and anti-epileptic drug responsiveness analysis, PIK3R1 and ITPR3 had significant differences in the hippocampus of patients with epilepsy." (PMID 39911741, 2024). "More significantly, PIK3R1 and ITPR3 were also significantly differentially expressed in the hippocampus of epilepsy group, compared with HC group." (PMID 39911741, 2024). "Therefore, PIK3R1 and ITPR3 had significant differences in peripheral blood and brain tissue of patients with epilepsy, and had potential as biomarkers in epilepsy." (PMID 39911741, 2024).
esophageal cancer (2 papers, 2017 to 2021). A primary or metastatic malignant neoplasm involving the esophagus. "In the esophageal cancer lesions, PIK3R1 was expressed in 65.5% (19/29) cases (+: 18; ++: 1; +++: 0), PTEN was expressed in 48.3% (15/31) cases (+: 14; ++: 1; +++: 0), and RASSF1 was expressed in 56.7% (17/30) cases (+: 14; ++: 3; +++: 0)." (PMID 27893424, 2017). "The biomarker potential of PIK3R1 methylation was also previously reported in esophageal cancer." (PMID 34944974, 2021).
idiopathic pulmonary fibrosis (2 papers, 2017 to 2022). Idiopathic pulmonary fibrosis (IPF) is a nonneoplastic pulmonary disease that is characterized by the formation of scar tissue within the lungs in the absence of any known cause. "miR-29b is a key repressor of renal and pulmonary fibrosis and has recently been shown to inhibit hepatic fibrogenesis by directly targeting PIK3R1 and AKT3 in hepatic stellate cells." (PMID 28174625, 2017). "protein–protein interaction protein interaction network analysis showed that PIK3CA, PIK3R1, MAPK1, SRC, AKT1, and so on may be the core targets of the compound Hongjingshen recipe in the treatment of pulmonary fibrosis." (PMID 36595795, 2022).
Inguinal hernia (2 papers, 2020 to 2025). Protrusion of the contents of the abdominal cavity through the inguinal canal. "We discovered that PIK3R1, PTPN11, TGFBR1, CDC42, SOS1, and KRAS were the most essential inguinal hernia-causative proteins and UBC, GRB2, CTNNB1, HSP90AA1, CBL, PLCG1, and CRK were listed as the most commonly-involved downstream proteins." (PMID 31910207, 2020). "Five essential proteins (PIK3R1, PTPN11, TGFBR1, CDC42, and SOS1) and three downstream common proteins (UBC, GRB2, and CTNNB1) were found to be related to inguinal hernia development." (PMID 31910207, 2020). "Thus, proteins PIK3R1, CDC42, TGFBR1, PTPN11, UBC, CTFR, and SOS1 may play an important role in the inguinal hernia PPI network." (PMID 31910207, 2020).
laryngeal squamous cell carcinoma (2 papers, 2020 to 2021). A squamous cell carcinoma that arises from the larynx. "Similar findings have been reported in laryngeal squamous cell carcinomas for other binomial LncRNA/mRNA transcripts, such as: NR_003919/PIK3R1, NR_027340/ITGB1, MIR31HG/HIF1A, and SOX2‐OT/DDIT4." (PMID 33433063, 2021).
leiomyosarcoma (2 papers, 2017 to 2021). An uncommon, aggressive malignant smooth muscle neoplasm, usually occurring in post-menopausal women. "Cancer and normal samples from different patient datasets showed that PIK3R1 expression was significantly lower in pleomorphic myxofibrosarcoma, myxofibrosarcoma, myxoid/round cell liposarcoma, leiomyosarcoma and malignant fibrous histiocytoma." (PMID 34741385, 2021).
lymph node metastases (2 papers, 2021 to 2023). "Compared to the samples without lymph node metastasis, ADRB2, DPYSL2, LIMCH1, and PIK3R1 were downregulated in samples with lymph node metastasis." (PMID 38057344, 2023). "Moreover, it was stated that the expression level of the PIK3CA, PIK3R1, PTEN, AKT1, mTOR genes does not depend on the patients’ age, lymph node metastases, ER, PR status and Ki-67 index." (PMID 33669698, 2021).
metastatic prostate carcinoma (2 papers, 2025). A carcinoma that arises from the prostate gland and has spread to other anatomic sites. "Dysregulation of the PI3K/AKT pathway, often driven by mutations in components such as PIK3R1, is associated with increased glycolysis and poor clinical outcomes in metastatic prostate cancer." (PMID 40429793, 2025).
nasopharyngeal carcinoma (2 papers, 2023 to 2024). A carcinoma arising from the nasopharyngeal epithelium. "Circ_0000215 could exert oncogenic effects in nasopharyngeal carcinoma through the miR-512-5p/PIK3R1 axis." (PMID 37298501, 2023).
prostate tumour (2 papers, 2010 to 2015). "A mutational profiling of AKT1 and of the mutational hotspots in PIK3CA and PIK3R1 was carried out in samples from primary and recurrent prostate tumours." (PMID 20407443, 2010). "We also analysed expression of PIK3R1 mRNA in 9 prostate tumour tissue samples relative to matched normal tissue from the same patient." (PMID 26501081, 2015). "PIK3R1 expression was significantly reduced in 6/9 prostate tumour tissue samples when compared with matched normal tissue from the same patient." (PMID 26501081, 2015).
renal fibrosis (2 papers, 2021 to 2022). A final common manifestation of a wide variety of chronic kidney diseases characterized by glomerulosclerosis and tubulointerstitial fibrosis. "Taken together, Quercetin could bind to PIK3R1 and inhibit the PI3k/Akt pathway, thereby minimizing renal fibrosis and apoptosis in CRF rats." (PMID 34528858, 2021). "Thus, the Quercetin might combine with PIK3R1 and minimize renal fibrosis and apoptosis in CRF rats by inhibiting the PI3k/Akt pathway." (PMID 34528858, 2021). "Taken together, Quercetin, a major component of SQJZJN, might minimize renal fibrosis and apoptosis in CRF rats by inhibiting the PI3k/Akt pathway through targeting PIK3R1." (PMID 34528858, 2021). "We constructed a regulatory network of SQJZJN-Quercetin-PIK3R1-CRF in a network pharmacological approach, investigated the target functions and molecular regulatory mechanisms to clarify the mechanisms of Quercetin on alleviating or delaying renal fibrosis." (PMID 34528858, 2021).